CGAS (cyclic GMP-AMP synthase)
Diseases named in the same sentence as CGAS in open-access papers (continued):
Sharing a sentence is not in itself a finding about the gene and the disease.
cancer (continued). "cGAS and STING deficiency in various cancer cell lines results in abolished or declined level of type I IFNs in response to exogenous cytosolic DNA, which may contribute to non-inflamed cancer microenvironment." (PMID 33790360, 2021). "TAMs are the main host cells for the occurrence of the cGAS-STING signal pathway in cancer." (PMID 34956229, 2021). "Because the cGAS–STING pathway is a key mediator of the immune response against cancer cells, this novel finding may lead to utilization of RNA Pol I inhibitors in combination with checkpoint inhibition." (PMID 34680204, 2021). "Considering that the activation of cGAS-STING signaling is implicated in some types of cancer, it is perspective that PAH may have an application in treating cancers." (PMID 33968056, 2021). "How is the cGAS-STING pathway playing an important role in cancer cell SASP induction upon RT?" (PMID 34079557, 2021). "The cGAS-STING pathway has recently provided insights into its influences on cancer development." (PMID 34858438, 2021). "In addition to PKR restriction, cGAS/STING DNA sensing is critical for limiting HSV infection, and recently, several studies have identified mechanisms in which cancer perturbs cGAS/STING signaling, providing an opportunity for Δγ134.5 oncolytic replication." (PMID 34372614, 2021). "Reduction of cytosolic DNA levels or cGAS deficiency did not restore cGAMP responsiveness of these cancer cells indicating that unresponsiveness was not caused by overstimulation of the pathway." (PMID 33790360, 2021). "In summary, our data show that cGAS binds to cytosolic dsDNA and to a lesser degree RNA:DNA hybrids in cancer cells, which may result in the activation of cGAS." (PMID 33790360, 2021). "Accordingly, since cancer cells have deregulated cell cycle checkpoints they frequently harbor cytoplasmic DNA, which is increased further upon genotoxic damage and radiotherapy exposure, and can lead to cGAS-STING activation;." (PMID 35087822, 2021). "In summary, cGAS-STING-elicited outcome in cancer is largely context-dependent." (PMID 34659260, 2021). "Recent research has demonstrated that cancers with high chromosomal instability (CIN) have increased levels of cytosolic DNA which contributes to endogenous cGAS/STING activation which, if sustained over time, can promote tumorigenesis, immune evasion and metastasis." (PMID 33572196, 2021). "To analyse if cGAS activity contributes to the dysfunction of STING in cGAMP unresponsive cancer cells, we inhibited cGAS expression by cGAS-specific siRNAs in DU145 and TRAMP-C2 cells or by a cGAS-specific RNA-guided Cas9 nuclease in A549, HeLa, and HCT116 cells." (PMID 33790360, 2021). "In addition, the cGAS-STING pathway has been involved in cancer immunity and the development of immunotherapies." (PMID 33708225, 2021). "Furthermore, exosomes shuttled from irradiated cancer cells to DCs promote IFN-I production via the cGAS/STING pathway in DCs." (PMID 35008367, 2021). "CIN, as a hallmark of cancer, has been linked to activation of key downstream biological pathways such as cGAS-STING and non-canonical nuclear factor κB (NF-κB)." (PMID 33997679, 2021). "Moreover, downregulation of cGAS and STING has been linked to higher susceptibility to OV infection among several cancer cell lines." (PMID 34203706, 2021). "Furthermore, there is still an important gap of knowledge on the cGAS-STING pathway role in cancer cell SASP induction upon RT." (PMID 34079557, 2021). "Prominent nuclear damage and genomic instability in cancer cells are further examples where the formation of micronuclei or mobilization of transposable genetic elements can feed the cytosol with DNA leading to cGAS activation and IFN-I production." (PMID 34084165, 2021).
cancer (continued). "ROS from radiation therapy or cell stress lead to cGAS-STING-mediated immune responses to cancer from DSBs as well as oxidative adducts that must be removed by DNA glycosylases, such as endonuclease VIII (Nei)-like proteins (NEIL) and oxoguanine DNA glycosylase (OGG1)." (PMID 34970273, 2021). "Additional findings confirm that the cGAS-STING pathway may regulate the immunogenicity of cancer cells." (PMID 34072037, 2021). "It has been found that the expression of these four essential molecular genes is significantly upregulated in almost all detected cancer types, suggesting that cGAS/STING signal transduction may be activated in all cancers." (PMID 35046953, 2021). "Furthermore, the responses of cancer cells to stresses are varied, and cancer therapy has been shown to induce senescence and activate the cGAS/STING pathway." (PMID 33558529, 2021). "The disconnection between specific type I or type III IFN expression and the induction of ISG expression is further supported by our finding that the response also occurs in cancer cells that lack either cGAS (cyclic GMP-AMP Synthase) or STING (Stimulator of interferon genes) expression." (PMID 33964942, 2021). "SLC19A1, a folate-organic phosphate antiporter, serves as the major transporter of cyclic dinucleotides, and its depletion and overexpression affect cyclic dinucleotide uptake and functional responses, which has implications for the immunotherapeutic treatment of cancer via cGAS-STING pathway." (PMID 33997099, 2021). "In addition, the chromosome missegregation in cancer cells ultimately leads to the leakage of DNA in the form of micronuclei, chromatin fragments and/or free telomere DNA, triggering the cGAS/STING signaling pathway." (PMID 35046953, 2021). "In addition to its role in anti-pathogenic surveillance and response, accumulating evidence suggests a key role for cGAS in immune activation in cancer cells." (PMID 33708225, 2021). "Compared to the STING protein, cGAS has been relatively underappreciated as a druggable target for cancer immunotherapy, despite the potential of a cGAS-targeting therapeutic to more closely mimic endogenous STING signaling by simulating natural, endogenous DNA sensing." (PMID 34899704, 2021). "The mechanism of how DNA repair defects may enhance ICI activity beyond the accumulation of somatic mutations remains to be elucidated, though impaired DNA repair mechanisms may modulate innate immune processes such as the cGAS-STING pathway in cancer cells." (PMID 32676589, 2020). "Further supporting the idea that the non-canonical pathway enhances cancer cell fitness is the observation that inactivating mutations in cGAS and STING are rarely found in breast or lung cancer cells." (PMID 32774773, 2020). "Obviously, targeted therapies to activate the cGAS-STING pathway in cancer cells can mediate cellular senescence and activate antitumor immunity, which could be another promising strategy for providing significant therapeutic benefits for cancer patients." (PMID 32355263, 2020). "However, many questions remain concerning the detailed regulation of cGAS‐mediated innate immunity and the impact on cancer immunotherapy." (PMID 32195086, 2020). "Due to the correlation between deficiencies in cGAS-STING pathway and surviving cancer cells, as well as the importance of cGAS-STING in the regulation of cancer-immunity cycle, STING agonists were developed to mimic this activation to enhance anti-cancer effects." (PMID 32571374, 2020). "Multiple cancer-causing viruses, such as KSHV, HBV, and HPV18, encode oncoproteins that disrupt cGAS-STING activity, which illustrates the evolutionary pressure on DNA tumor viruses to develop functions against this pathway and its importance in carcinogenesis." (PMID 33109261, 2020). "These outcomes show that initiation of the cGAS pathway is essential for fundamental antitumor immunity and that cGAMP might be utilized straightforwardly for cancer immunotherapy." (PMID 32195086, 2020).
cancer (continued). "However, opposite roles of cGAS–STING signaling in cancer development and metastasis have been reported." (PMID 32382015, 2020). "Therefore, it is necessary to fully evaluate the function of cGAS/STING signaling in cancer immunity before the application of the STING agonist-based anticancer immune therapy." (PMID 35006429, 2020). "In addition to cancer cells, activation of cGAS-STING pathway in immune cells also contributes to antitumor activities." (PMID 33633744, 2020). "Regardless, because ALK fusion genes are associated with several types of cancer and these findings suggest a possible role for ALK in cGAS-STING signaling, the relationship between ALK-EGFR-AKT and components of the STING pathway ought to be thoroughly examined with further studies." (PMID 32774773, 2020). "However, further studies depending on the race, genetics, and sex of patients, are crucial before using cGAS-STING modulators in different cancers." (PMID 33643304, 2020). "In addition to cancer, the cGAS-STING pathway holds a promising role for the treatment of autoimmune or inflammatory diseases." (PMID 33081170, 2020). "STING suppression offers another way in which cancer cells can evade cGAS-STING signaling." (PMID 32774773, 2020). "Thus, enhancing cGAS‐STING signaling leading to type I IFN production represents a promising therapeutic approach for cancer treatment." (PMID 33179413, 2020). "cGAS also promotes cancer progression by inhibiting DNA repair and may also rewire the STING pathway to promote metastasis, while avoiding IFNβ production." (PMID 32516941, 2020). "Consistent with the pathogenic role of dysregulated type I IFN production, human gain-of-function mutations in STING lead to systemic inflammation, whereas excessive cGAS-STING signaling in response to either self or pathogen DNA is now linked to multiple diseases, including cancers." (PMID 32102850, 2020). "Understanding the mechanisms involved in producing immune responses against cancer following radiotherapy, as well as how activation or inhibition of key players involved in cGAS–STING signaling affects antitumor efficacy, will aid in informing strategies to improve radiotherapy." (PMID 33238631, 2020). "Furthermore, developing a more effective delivery system and designing rational cGAS-STING agonists are coordinatively important for improving cancer therapeutic effect." (PMID 32887628, 2020). "In sum, the cGAS-STING pathway shows invaluable potentials in cancer biotherapy." (PMID 32887628, 2020). "However, there is a higher frequency of cGAS/STING gene promoter silencing by hypermethylation in cancer cells as compared with WT cells." (PMID 32774773, 2020). "Furthermore, DNA from cancer cells can be transferred into DC cytoplasm and activate cGAS-STING-type I IFN pathway, which is critical to subsequent activation of T cells." (PMID 32296457, 2020). "cGAS-driven extracellular export of 2′3′ cGAMP by cancer cells activates STING signaling in endothelial cells and cooperates with type 1 interferon to increase vascular permeability and expression of E selectin, VCAM-1, and ICAM-1 and T cell adhesion to the endothelium." (PMID 33013881, 2020). "Indeed, many studies have endeavored to harness the potency of cGAS-mediated immune response in cancer treatment." (PMID 32774773, 2020). "We believe cGAS-STING pathway manipulation might become a promising strategy combined with cancer immunotherapy." (PMID 32571374, 2020). "Moreover, cGAS provides additional antitumor roles by detecting DNA damage in premalignant cells or in cancer cells treated with classic cancer therapies." (PMID 32541866, 2020). "Thus, the RLR–MAVS pathway is functional in most human epithelial cancer cells, but the cGAS–STING pathway is inactive." (PMID 33490069, 2020).
cancer (continued). "Also, several publications suggest that cGAS-cGAMP-STING pathway play a significant role during cancer immune evasion and immune system stimulation process." (PMID 31120925, 2019). "In general, cGAS-STING signaling pathway is favorable to anti-cancer immune response." (PMID 30935414, 2019). "It is generally believed that cancer-derived DNA could get in DC cytoplasm and stimulate cGAS-STING-type I IFN pathway, which is essential to subsequent activation of T cell." (PMID 30935414, 2019). "Therefore, the pharmacological activation of cGAS-STING pathway would be a potential cancer treatment strategy." (PMID 30935414, 2019). "The results of co-culture of cancer cells and effector cells showed that cancer cells with downregulated cGAS-STING pathway could resist to immune killing." (PMID 30935414, 2019). "Even though cGAS-STING pathway could induce the activation of apoptosis pathway in cancer cell, the pro-apoptosis role of cGAS-STING remains to be further determined in immune cells." (PMID 30935414, 2019). "Similar as described for chemotherapeutics, radiotherapy will trigger cGAS-STING signaling through the generation of neo-epitopes that will activate dendritic cells, and through the accumulation of cytoplasmic DNA that will directly trigger cGAS-STNG in the cancer cells." (PMID 31658669, 2019). "When radiation was delivered at a high dose, the induction of three prime repair exonuclease 1 (Trex1) in irradiated cancer cells can degrade the DNA accumulating in the cytosol, which precluded the activation of cGAS-STING-IFN-I pathway and dampens the radiation-induced immunostimulation." (PMID 31695799, 2019). "Additionally, the cGAS /STING pathway in irradiated cancer cells stimulates the production of IFN I, which is critical in the abscopal response." (PMID 31261963, 2019). "Upon entry into the nucleus, cGAS interacts with PARP1 and inhibits the formation of PARP1-Timeless complex, thereby suppressing homologous recombination-mediated DNA repair and promoting tumorigenesis, indicative of cGAS as a novel therapeutic target for cancer." (PMID 30937856, 2019). "Recently, a series of studies demonstrated that the vital component of host innate immunity — cGAS-STING pathway might play an important role in anti-cancer immunity." (PMID 30935414, 2019). "We believe manipulating cGAS-STING pathway might be a promising synergistic strategy with cancer immunotherapy." (PMID 30935414, 2019). "However, cGAS-STING was also observed as an inhibitory component in cancer immune microenvironment in some studies." (PMID 30935414, 2019). "Therefore, intact cGAS-STING pathway is an important regulator of cancer cell growth, senescence, and immune surveillance." (PMID 30935414, 2019). "Depletion of cGAS in cancer cells was found to inhibit the growth of brain metastases." (PMID 31114634, 2019). "The cGAS-STING signaling axis adds another layer of complexity to the role of CIN in cancer." (PMID 31658669, 2019). "cGAS/STING pathway has the potential to be targeted for effective cancer therapeutics." (PMID 29156566, 2017). "Damaged genomic DNA caused by carcinogens like DMBA, cisplatin, etoposide or radiation and mitochondrial DNA leakage has been shown to be the primal sources of the cytoplasmic DNA in cancer cells that can potentially activate cGAS/STING mediated immune response." (PMID 29156566, 2017). "It should also be mentioned that the carcinogenic effect of cGAS/STING signaling may be cancer type specific." (PMID 29156566, 2017). "Selection against cGAS–STING-dependent inflammatory signalling during cancer progression may be a major factor shaping drug responses." (PMID 29142107, 2017). "Therefore, cGAS can be activated by endogenous DNA specifically in human ecDNA+ cancer cells." (PMID 41509453, 2026). "Therefore, ectopically expressed cGAS can be activated in ecDNA+ mouse cancer cells." (PMID 41509453, 2026).
cancer (continued). "Therefore, exploring the cGAS-STING pathway in clinical samples might be useful for understanding the nature of cancer." (PMID 40786100, 2025). "Moreover, the results of the present study suggest that CIN-dependent activation of cGAS–STING signaling may contribute to cancer cell proliferation under EGFR-TKI treatment in a subset of EGFR-mutated NSCLC tumors." (PMID 40136696, 2025). "The complete loss of the CGAS-STING1 pathway in armadillos suggests this lineage has evolved alternate ways to sense intracellular double-stranded DNA, which may be related to their extreme cancer resistance." (PMID 40463121, 2025). "Additionally, STING knockout in HNSCC cells has been shown to disrupt the crosstalk between natural killer cells and dendritic cells (DCs) in an in vitro setting, further underscoring the importance of the cancer cell-initiated cGAS-IFN-I signaling in inducing favorable antitumor immune responses." (PMID 40282455, 2025). "However, since activating the cGAS‐STING pathway through damaged DNA is unfavorable for cancer cells, many tumors have developed diverse strategies to evade detection and suppress the immune response with the primary objective of stabilizing the genome and prevent MN formation[33a]." (PMID 40145387, 2025). "Moreover, protumorigenic effects of the cGAS/STING pathway were observed in some cancer models." (PMID 41129257, 2025). "However, in cancer cells various defects result in the presence of self-nucleic acids in the cytoplasm, causing the induction of type I IFN signaling, mainly through the cGAS/STING axis." (PMID 40098954, 2025). "Moreover, evidence for preferential activation of the immune-suppressive non-canonical NFkB pathway downstream of cGAS-STING has been shown in some cancers with CIN, and is associated with reduced survival." (PMID 40500315, 2025). "Therefore, targeting the cGAS-STING pathway to enhance cancer immunotherapy may be an option for cancer treatment." (PMID 40643531, 2025). "Therefore, we hypothesize that in liver metastasis, carcinoma cells pass through the capillaries leading to nuclear deformation and cGAS activation." (PMID 39737867, 2025). "Nevertheless, innate immune cells are major type I IFN producers that influence cancer immunosurveillance, therefore it is important to understand the cGAS-STING pathway mechanisms in these cells and whether it can be modulated indirectly by factors present in the TME." (PMID 38389103, 2024). "Therefore, we analyzed whether radiotherapy activated cGAS/STING signaling to increase the clinical efficacy of iPSC-based cancer vaccines." (PMID 38821980, 2024). "Consequently, cGAS-activating cancer cells can produce high levels of the immunotransmitter cGAMP." (PMID 38413714, 2024). "In summary, advancements in cGAS stimulators, such as Svg3, manganese, and eribulin, as well as the emergence of nanocomposites for targeted drug delivery have proven promising for enhancing immune responses against diseases, particularly cancers, by effectively targeting the cGAS-STING pathway." (PMID 39050748, 2024). "However, the activation of cGAS/STING in cancer cells remains a major challenge." (PMID 38868091, 2024). "Moreover, combinatorial treatments with DNA damage response (DDR) inhibitors may sensitize cancer cells to radiation treatment by activating the cGAS/STING and RIG-I/MAVS pathways." (PMID 39372406, 2024). "Moreover, cGAS protein also highly detected in cancer cells and stem and immune cells, indicating that cGAS might play important roles in not only immune response, but also in unknown functions, such as chromatin remodeling." (PMID 39424777, 2024). "Identifying compounds that boost cGAS-STING activity could be beneficial for cancer treatment." (PMID 39170700, 2024).